CCDC169 (coiled-coil domain containing 169)
Synonyms: C13orf38; RP11-251J8.1; LOC728591
Tractability: No criterion of Open Targets' tractability assessment is met for any kind of drug.
Gene: Protein-coding gene on chromosome 13 (36,222,008 to 36,297,840, reverse strand). Ensembl gene ENSG00000242715.
Subcellular location (Human Protein Atlas): Nucleoplasm; Nuclear speckles; Vesicles
Genetic constraint (gnomAD): Loss-of-function variants: 25 observed, 30.05 expected, observed/expected ratio (o/e) 0.83, 90% interval 0.61 to 1.16. The upper end of that interval is the gene's LOEUF score, 1.16, which puts it in group 5 of 6, group 1 being the genes least tolerant of losing a copy. Missense variants: 209 observed, 219.13 expected, observed/expected ratio (o/e) 0.95, 90% interval 0.85 to 1.07. Synonymous variants: 72 observed, 72.5 expected, observed/expected ratio (o/e) 0.99, 90% interval 0.82 to 1.21.
Homologues: Orthologues: chimpanzee CCDC169 (86% identical), rabbit CCDC169 (72% identical), guinea pig CCDC169 (72% identical), mouse Ccdc169 (71% identical), rat Ccdc169 (68% identical).
Diseases named in the same sentence as CCDC169 in open-access papers:
CCDC169 is named in the same sentence as 4 diseases in open-access papers, as found by Europe PMC text mining. Sharing a sentence is not in itself a finding about the gene and the disease. The quoted sentences say what the papers report.
colorectal cancer (1 paper, 2023). A primary or metastatic malignant neoplasm that affects the colon or rectum. "Another chosen gene CCDC169 is located in cytoband 13q13.3 and correlated with chromosomal aneuploidy in colorectal cancer cells." (PMID 37903125, 2023).
gastric cancer (1 paper, 2022). A primary or metastatic malignant neoplasm involving the stomach. "Five mutated genes, KNL1, NRXN1, C6, CCDC169-SOHLH2, and TTN, showed a significant negative correlation with the recurrence of gastric cancer through multivariable logistic regression analysis." (PMID 35187167, 2022). "In the present study, we analyzed the DNA sequencing data of 229 patients from the TCGA-STAD project and identified five potential driver genes (CCDC169-SOHLH2, TTN, KNL1, C6, NRXN1) whose mutations were negatively associated with gastric cancer recurrence (p < 0.01)." (PMID 35187167, 2022).
CCDC169 also shares sentences with these, for which no sentence is quoted: glioma (1 paper); thrombosis (1).